SIRT1 (sirtuin 1)
Description:
NAD-dependent protein deacetylase that links transcriptional regulation directly to intracellular energetics and participates in the coordination of several separated cellular functions such as cell cycle, response to DNA damage, metabolism, apoptosis and autophagy. Can modulate chromatin function through deacetylation of histones and can promote alterations in the methylation of histones and DNA, leading to transcriptional repression. Deacetylates a broad range of transcription factors and coregulators, thereby regulating target gene expression positively and negatively. Serves as a sensor of the cytosolic ratio of NAD(+)/NADH which is altered by glucose deprivation and metabolic changes associated with caloric restriction. Is essential in skeletal muscle cell differentiation and in response to low nutrients mediates the inhibitory effect on skeletal myoblast differentiation which also involves 5'-AMP-activated protein kinase (AMPK) and nicotinamide phosphoribosyltransferase (NAMPT) (By similarity). Component of the eNoSC (energy-dependent nucleolar silencing) complex, a complex that mediates silencing of rDNA in response to intracellular energy status and acts by recruiting histone-modifying enzymes. The eNoSC complex is able to sense the energy status of cell: upon glucose starvation, elevation of NAD(+)/NADP(+) ratio activates SIRT1, leading to histone H3 deacetylation followed by dimethylation of H3 at 'Lys-9' (H3K9me2) by SUV39H1 and the formation of silent chromatin in the rDNA locus. Deacetylates 'Lys-266' of SUV39H1, leading to its activation. Inhibits skeletal muscle differentiation by deacetylating PCAF and MYOD1. Deacetylates H2A and 'Lys-26' of H1-4. Deacetylates 'Lys-16' of histone H4 (in vitro). Involved in NR0B2/SHP corepression function through chromatin remodeling: Recruited to LRH1 target gene promoters by NR0B2/SHP thereby stimulating histone H3 and H4 deacetylation leading to transcriptional repression. Proposed to contribute to genomic integrity via positive regulation of telomere length; however, reports on localization to pericentromeric heterochromatin are conflicting (By similarity). Proposed to play a role in constitutive heterochromatin (CH) formation and/or maintenance through regulation of the available pool of nuclear SUV39H1. Upon oxidative/metabolic stress decreases SUV39H1 degradation by inhibiting SUV39H1 polyubiquitination by MDM2. This increase in SUV39H1 levels enhances SUV39H1 turnover in CH, which in turn seems to accelerate renewal of the heterochromatin which correlates with greater genomic integrity during stress response. Deacetylates TAF1B and thereby represses rDNA transcription by the RNA polymerase I (By similarity). Deacetylates MYC, promotes the association of MYC with MAX and decreases MYC stability leading to compromised transformational capability. Deacetylates FOXO3 in response to oxidative stress thereby increasing its ability to induce cell cycle arrest and resistance to oxidative stress but inhibiting FOXO3-mediated induction of apoptosis transcriptional activity; also leading to FOXO3 ubiquitination and protesomal degradation. Appears to have a similar effect on MLLT7/FOXO4 in regulation of transcriptional activity and apoptosis. Deacetylates DNMT1; thereby impairs DNMT1 methyltransferase-independent transcription repressor activity, modulates DNMT1 cell cycle regulatory function and DNMT1-mediated gene silencing. Deacetylates RELA/NF-kappa-B p65 thereby inhibiting its transactivating potential and augments apoptosis in response to TNF. Deacetylates HIF1A, KAT5/TIP60, RB1 and HIC1. Deacetylates FOXO1 resulting in its nuclear retention and enhancement of its transcriptional activity leading to increased gluconeogenesis in liver. Inhibits E2F1 transcriptional activity and apoptotic function, possibly by deacetylation. Involved in HES1- and HEY2-mediated transcriptional repression. In cooperation with MYCN seems to be involved in transcriptional repression of DUSP6/MAPK3 leading to MYCN stabilization by phosphorylation at 'Ser-62'. Deacetylates MEF2D. Required for antagonist-mediated transcription suppression of AR-dependent genes which may be linked to local deacetylation of histone H3. Represses HNF1A-mediated transcription (By similarity). Required for the repression of ESRRG by CREBZF. Deacetylates NR1H3 and NR1H2 and deacetylation of NR1H3 at 'Lys-434' positively regulates transcription of NR1H3:RXR target genes, promotes NR1H3 proteasomal degradation and results in cholesterol efflux; a promoter clearing mechanism after reach round of transcription is proposed. Involved in lipid metabolism: deacetylates LPIN1, thereby inhibiting diacylglycerol synthesis. Implicated in regulation of adipogenesis and fat mobilization in white adipocytes by repression of PPARG which probably involves association with NCOR1 and SMRT/NCOR2 (By similarity). Deacetylates p300/EP300 and PRMT1 (By similarity). Deacetylates ACSS2 leading to its activation, and HMGCS1 deacetylation. Involved in liver and muscle metabolism. Through deacetylation and activation of PPARGC1A is required to activate fatty acid oxidation in skeletal muscle under low-glucose conditions and is involved in glucose homeostasis. Involved in regulation of PPARA and fatty acid beta-oxidation in liver. Involved in positive regulation of insulin secretion in pancreatic beta cells in response to glucose; the function seems to imply transcriptional repression of UCP2. Proposed to deacetylate IRS2 thereby facilitating its insulin-induced tyrosine phosphorylation. Deacetylates SREBF1 isoform SREBP-1C thereby decreasing its stability and transactivation in lipogenic gene expression. Involved in DNA damage response by repressing genes which are involved in DNA repair, such as XPC and TP73, deacetylating XRCC6/Ku70, and facilitating recruitment of additional factors to sites of damaged DNA, such as SIRT1-deacetylated NBN can recruit ATM to initiate DNA repair and SIRT1-deacetylated XPA interacts with RPA2. Also involved in DNA repair of DNA double-strand breaks by homologous recombination and specifically single-strand annealing independently of XRCC6/Ku70 and NBN. Promotes DNA double-strand breaks by mediating deacetylation of SIRT6. Transcriptional suppression of XPC probably involves an E2F4:RBL2 suppressor complex and protein kinase B (AKT) signaling. Transcriptional suppression of TP73 probably involves E2F4 and PCAF. Deacetylates WRN thereby regulating its helicase and exonuclease activities and regulates WRN nuclear translocation in response to DNA damage. Deacetylates APEX1 at 'Lys-6' and 'Lys-7' and stimulates cellular AP endonuclease activity by promoting the association of APEX1 to XRCC1. Catalyzes deacetylation of ERCC4/XPF, thereby impairing interaction with ERCC1 and nucleotide excision repair (NER). Deacetylates XRCC6/Ku70 at 'Lys-539' and 'Lys-542' causing it to sequester BAX away from mitochondria thereby inhibiting stress-induced apoptosis. Is involved in autophagy, presumably by deacetylating ATG5, ATG7 and MAP1LC3B/ATG8. Deacetylates AKT1 which leads to enhanced binding of AKT1 and PDK1 to PIP3 and promotes their activation. Acts as a regulator of AMPK activity in response to calorie restriction: deacetylates the ATP6V1E1 subunit of the V-ATPase complex following activation by TULP3, leading to (1) V-ATPase complex inhibition on lysosomes and (2) AMPK activation via the AXIN1-STK11/LKB1 axis (By similarity). Proposed to play role in regulation of STK11/LBK1-dependent AMPK signaling pathways implicated in cellular senescence which seems to involve the regulation of the acetylation status of STK11/LBK1. Can deacetylate STK11/LBK1 and thereby increase its activity, cytoplasmic localization and association with STRAD; however, the relevance of such activity in normal cells is unclear. In endothelial cells is shown to inhibit STK11/LBK1 activity and to promote its degradation. Deacetylates SMAD7 at 'Lys-64' and 'Lys-70' thereby promoting its degradation. Deacetylates CIITA and augments its MHC class II transactivation and contributes to its stability. Deacetylates MECOM/EVI1. Deacetylates PML at 'Lys-487' and this deacetylation promotes PML control of PER2 nuclear localization. During the neurogenic transition, represses selective NOTCH1-target genes through histone deacetylation in a BCL6-dependent manner and leading to neuronal differentiation. Regulates the circadian expression of several core clock genes, including BMAL1, RORC, PER2 and CRY1 and plays a critical role in maintaining a controlled rhythmicity in histone acetylation, thereby contributing to circadian chromatin remodeling. Deacetylates BMAL1 and histones at the circadian gene promoters in order to facilitate repression by inhibitory components of the circadian oscillator (By similarity). Deacetylates PER2, facilitating its ubiquitination and degradation by the proteasome (By similarity). Protects cardiomyocytes against palmitate-induced apoptosis (By similarity). Deacetylates XBP1 isoform 2; deacetylation decreases protein stability of XBP1 isoform 2 and inhibits its transcriptional activity. Deacetylates PCK1 and directs its activity toward phosphoenolpyruvate production promoting gluconeogenesis. Involved in the CCAR2-mediated regulation of PCK1 and NR1D1. Deacetylates CTNB1 at 'Lys-49'. In POMC (pro-opiomelanocortin) neurons, required for leptin-induced activation of PI3K signaling (By similarity). Deacetylates SOX9; promoting SOX9 nuclear localization and transactivation activity (By similarity). Involved in the regulation of centrosome duplication: deacetylates CENATAC in G1 phase, allowing for SASS6 accumulation on the centrosome and subsequent procentriole assembly. Deacetylates NDC80/HEC1. In addition to protein deacetylase activity, also acts as a protein-lysine deacylase by mediating protein delactylation, depropionylation and decrotonylation. Mediates depropionylation of Osterix (SP7) (By similarity). Catalyzes decrotonylation of histones; it however does not represent a major histone decrotonylase. Mediates protein delactylation of TEAD1 and YAP1. In combination, the two isoforms exert an additive effect. [SirtT1 75 kDa fragment]: Catalytically inactive 75SirT1 may be involved in regulation of apoptosis. May be involved in protecting chondrocytes from apoptotic death by associating with cytochrome C and interfering with apoptosome assembly. (Microbial infection) In case of HIV-1 infection, interacts with and deacetylates the viral Tat protein. The viral Tat protein inhibits SIRT1 deacetylation activity toward RELA/NF-kappa-B p65, thereby potentiates its transcriptional activity and SIRT1 is proposed to contribute to T-cell hyperactivation during infection.
Synonyms: SIR2L1; SIR2; SIR2alpha
Tractability: Small molecule: a drug acting on it is in phase 2 or 3 trials; a structure with a bound ligand is known; a high-quality ligand is known; it belongs to a druggable protein family. PROTAC: UniProt records ubiquitination sites on it; ubiquitination databases record sites on it; its protein half-life has been measured; a small molecule that binds it is known.
Target class: Histone deacetylase; HDAC class III; Epigenetic regulator; Eraser
Gene: Protein-coding gene on chromosome 10 (67,884,656 to 67,918,390, forward strand). Ensembl gene ENSG00000096717.
Subcellular location: Nucleus, PML body; Cytoplasm; Nucleus; Cytoplasm (SirtT1 75 kDa fragment); Mitochondrion
Subcellular location (Human Protein Atlas): Nucleoplasm; Cytosol; Mitochondria; Nucleoli fibrillar center
Pathways (Reactome):
Gene expression (Transcription): MLL4 and MLL3 complexes regulate expression of PPARG target genes in adipogenesis and hepatic steatosis; Regulation of FOXO transcriptional activity by acetylation; SIRT1 negatively regulates rRNA expression
Cellular responses to stimuli: Heme signaling; Regulation of HSF1-mediated heat shock response
Developmental Biology: Regulation of MITF-M dependent genes involved in metabolism; Transcriptional and post-translational regulation of MITF-M expression and activity
Cell-Cell communication: Negative Regulation of CDH1 Gene Transcription
Circadian clock: Expression of BMAL (ARNTL), CLOCK, and NPAS2
Gene Ontology:
Molecular function: bHLH transcription factor binding; deacetylase activity; DNA-binding transcription factor binding; enzyme activator activity; enzyme binding; histone binding; histone deacetylase activity; histone deacetylase activity, NAD-dependent; histone decrotonylase activity, NAD-dependent; histone H3K deacetylase activity; histone H3K14 deacetylase activity, NAD-dependent; histone H3K9 deacetylase activity, NAD-dependent; histone H4K12 deacetylase activity, hydrolytic mechanism; histone H4K16 deacetylase activity, NAD-dependent; HLH domain binding; identical protein binding; keratin filament binding; mitogen-activated protein kinase binding; NAD-dependent protein decrotonylase activity; NAD-dependent protein lysine deacetylase activity; NAD-dependent protein lysine delactylase activity; nuclear receptor binding; protein binding; protein lysine deacetylase activity; and 11 more
Biological process: angiogenesis; cellular response to glucose starvation; cellular response to hydrogen peroxide; cellular response to hypoxia; cellular response to tumor necrosis factor; chromatin organization; circadian regulation of gene expression; DNA damage response; DNA repair-dependent chromatin remodeling; endoplasmic reticulum unfolded protein response; energy homeostasis; heterochromatin formation; maintenance of nucleus location; negative regulation of androgen receptor signaling pathway; negative regulation of apoptotic process; negative regulation of canonical NF-kappaB signal transduction; negative regulation of cell cycle; negative regulation of cellular response to testosterone stimulus; negative regulation of cellular senescence; negative regulation of DNA-templated transcription; negative regulation of gene expression; negative regulation of hippo signaling; negative regulation of oxidative stress-induced intrinsic apoptotic signaling pathway; and 85 more
Cellular component: chromatin; chromatin silencing complex; cytoplasm; cytosol; eNoSc complex; ESC/E(Z) complex; euchromatin; heterochromatin; mitochondrion; nuclear envelope; nuclear inner membrane; nucleolus; nucleoplasm; nucleus; PML body; rDNA heterochromatin; chromosome, telomeric region; protein-containing complex
Genetic constraint (gnomAD): Loss-of-function variants: 21 observed, 57.41 expected, observed/expected ratio (o/e) 0.37, 90% interval 0.26 to 0.53. The upper end of that interval is the gene's LOEUF score, 0.53, which puts it in group 2 of 6, group 1 being the genes least tolerant of losing a copy. Missense variants: 840 observed, 875.49 expected, observed/expected ratio (o/e) 0.96, 90% interval 0.91 to 1.02. Synonymous variants: 362 observed, 325.75 expected, observed/expected ratio (o/e) 1.11, 90% interval 1.02 to 1.21.
Gene-disease validity (ClinGen):
ClinGen rates the evidence that SIRT1 causes each of these diseases.
monogenic diabetes (autosomal dominant): Limited. Diabetes mellitus that is caused by mutations in a single gene.
Homologues: Orthologues: chimpanzee SIRT1 (99% identical), macaque SIRT1 (97% identical), pig SIRT1 (91% identical), rabbit SIRT1 (91% identical), rat Sirt1 (88% identical), mouse Sirt1 (86% identical), guinea pig SIRT1 (84% identical), tropical clawed frog sirt1 (56% identical), zebrafish sirt1 (50% identical), Drosophila melanogaster Sirt1 (38% identical), Caenorhabditis elegans sir-2.1 (29% identical). Paralogues in human: SIRT2 (19% identical), SIRT3 (16% identical), SIRT5 (11% identical), SIRT7 (10% identical), SIRT4 (10% identical), SIRT6 (9% identical).
Diseases named in the same sentence as SIRT1 in open-access papers:
SIRT1 is named in the same sentence as 803 diseases in open-access papers, as found by Europe PMC text mining. Sharing a sentence is not in itself a finding about the gene and the disease. The quoted sentences say what the papers report.